H2AC13 (H2A clustered histone 13)
Description:
Core component of nucleosome. Nucleosomes wrap and compact DNA into chromatin, limiting DNA accessibility to the cellular machineries which require DNA as a template. Histones thereby play a central role in transcription regulation, DNA repair, DNA replication and chromosomal stability. DNA accessibility is regulated via a complex set of post-translational modifications of histones, also called histone code, and nucleosome remodeling.
Synonyms: H2AFC; HIST1H2AI; H2A/c
Tractability: Small molecule: a structure with a bound ligand is known. PROTAC: UniProt records ubiquitination sites on it; ubiquitination databases record sites on it.
Gene: Protein-coding gene on chromosome 6 (27,808,173 to 27,808,667, forward strand). Ensembl gene ENSG00000196747.
Subcellular location: Nucleus; Chromosome
Subcellular location (Human Protein Atlas): Nucleoplasm
Pathways (Reactome):
Chromatin organization: HATs acetylate histones; HDACs deacetylate histones; RMTs methylate histone arginines
Disease: Dengue Virus-Host Interactions; HCMV Early Events; HCMV Late Events
Metabolism of proteins: Metalloprotease DUBs; UCH proteinases; Ub-specific processing proteases
Gene Ontology:
Molecular function: enzyme binding; protein binding; structural constituent of chromatin; DNA binding; protein heterodimerization activity
Biological process: chromatin organization; heterochromatin formation
Cellular component: extracellular exosome; nucleoplasm; nucleosome; nucleus; chromosome
Genetic constraint (gnomAD): Loss-of-function variants: 3 observed, 5.37 expected, observed/expected ratio (o/e) 0.56, 90% interval 0.25 to 1.41. That is too few expected variants to judge how well the gene tolerates losing a copy. Missense variants: 123 observed, 168.95 expected, observed/expected ratio (o/e) 0.73, 90% interval 0.63 to 0.85. Synonymous variants: 96 observed, 76.42 expected, observed/expected ratio (o/e) 1.26, 90% interval 1.06 to 1.49.
Homologues: Orthologues: Drosophila melanogaster His2A:CG31618 (85% identical), Drosophila melanogaster His2A:CG33808 (85% identical), Drosophila melanogaster His2A:CG33814 (85% identical), Drosophila melanogaster His2A:CG33817 (85% identical), Drosophila melanogaster His2A:CG33820 (85% identical), Drosophila melanogaster His2A:CG33823 (85% identical), Drosophila melanogaster His2A:CG33826 (85% identical), Drosophila melanogaster His2A:CG33829 (85% identical), Drosophila melanogaster His2A:CG33832 (85% identical), Drosophila melanogaster His2A:CG33835 (85% identical), Drosophila melanogaster His2A:CG33838 (85% identical), Drosophila melanogaster His2A:CG33841 (85% identical), and 8 more. Paralogues in human: H2AC11 (100% identical), H2AC15 (100% identical), H2AC16 (100% identical), H2AC17 (100% identical), H2AC7 (99% identical), H2AC12 (98% identical), H2AC18 (98% identical), H2AC19 (98% identical), H2AC4 (98% identical), H2AC6 (98% identical), H2AC8 (98% identical), H2AC14 (98% identical), and 15 more.
Diseases named in the same sentence as H2AC13 in open-access papers:
H2AC13 is named in the same sentence as 8 diseases in open-access papers, as found by Europe PMC text mining. Sharing a sentence is not in itself a finding about the gene and the disease.
H2AC13 shares sentences with these, for which no sentence is quoted: Alpha-thalassemia (1 paper); anemia (1); breast carcinoma (1); cancer (1); Diamond-Blackfan anemia (1); Fanconi anemia (1); microcytic anemia (1); systemic lupus erythematosus (1).